BCL2 (BCL2 apoptosis regulator)
Diseases named in the same sentence as BCL2 in open-access papers (continued):
Sharing a sentence is not in itself a finding about the gene and the disease.
cancer (continued). "The dose dependent down regulation of Bcl-2 in treated cells demonstrated that saponin fraction can trigger intrinsic apoptotic pathway in cancer cells." (PMID 28496480, 2017). "Anti-apoptotic Bcl-2 protects cancer cells from cell death by acting at the mitochondria, scaffolding Bim/Bak/Bax and by acting at the ER, suppressing excessive IP3Rs activity." (PMID 29340082, 2017). "Downregulation of Bcl-2 increased chemosensitivity in clinical studies in a wide variety of cancers." (PMID 28464919, 2017). "The balance of Bax and Bcl-2 in cells plays a pivotal role in the regulation of apoptosis in LCSE-treated cancer cells which was highlighted in our previous report and other studies." (PMID 28056952, 2017). "For instance, one of the experimental drug candidates for the treatment of various types of cancer is obatoclax, which is a pan-inhibitor of the anti-apoptotic Bcl-2 protein." (PMID 28754836, 2017). "As estimated to be potent regulator in cell apoptosis by specifically targeting Bcl-2, miR-181a has been subjected to diverse level of tests in many different cancers and its functions are well documented." (PMID 29041990, 2017). "The quantitative real-time polymerase chain reaction (qRT-PCR), western blot, and dual-luciferase assays indicate that PBP1 upregulates and PBP2 downregulates BCL-2 gene expression in cancer cells." (PMID 29163897, 2017). "ROS accumulation in cancer cells causes nitration and inactivation of PP2A, which interferes with the interaction of Bcl-2 with the PP2A catalytic core, leading to increased phosphorylation and antiapoptotic activity of Bcl-2." (PMID 28282450, 2017). "Basically, NF-kBs affect cell survival and proliferation in cancer by inducing expression of genes coding for key anti-apoptotic proteins, such as Bcl-2 and IAP-1/2 and mitogenic genes, such as myc and cyclin-D." (PMID 27145266, 2017). "The antiapoptotic B‐cell lymphoma 2 (BCL2) gene is a key player in cancer development and progression." (PMID 28396899, 2017). "Severely decreased ECHS1, accumulation of BCAAs and FAs, activation of mTOR and overexpression of BCL-2 were observed in cancer tissues from metabolic organs." (PMID 28878358, 2017). "VDAC1 also regulates apoptosis via interactions with apoptosis regulatory proteins, such as hexokinase, Bcl2 and Bcl-xL, some of which are also highly expressed in many cancers." (PMID 30542671, 2017). "Bcl-2 and Bcl-xL proteins are overexpressed in a variety of human cancers, and function as suppressors of apoptosis, resulting in the survival of malignant cells." (PMID 28545243, 2017). "Previous reports have shown that activation of STAT3 reduces the apoptotic effect of chemotherapeutic drugs in various cancer cells by up-regulating Bcl-2 and Bcl-xL." (PMID 28114390, 2017). "Cancer cells generally overexpress antiapoptotic factors, such as Bcl-2, in order to reduce the intrinsic apoptosis signaling." (PMID 28545243, 2017). "Cancer is initiated when there is an upregulation of anti-apoptotic genes (including Bcl-2) and downregulation of pro-apoptotic genes (containing Bax)." (PMID 28545028, 2017). "Overall, these results demonstrate the decreasing the ratio of Bcl-2/Bax in 9f-treated HL-60 cancer cells." (PMID 28814788, 2017). "The positive expression rates of Bcl-2 in carcinoma and sarcomatoid cells were 60% (25/42) and 21% (9/42), respectively (P = 0.001)." (PMID 28449664, 2017).
cancer (continued). "Analysis of carcinoma cells in animals showed bcl‐2, Ki67, VEGFA, CD24 and CD44 expression decrease and Bax, caspase‐3 and ALDH1 expression increase after high‐dose CLO administration." (PMID 28524540, 2017). "mRNA for anti-apoptotic Bcl-2 was decreased and that for pro-apoptotic Bax was increased in the carcinoma tissue of CR, l-1-deoxynojirimycin and H-1-deoxynojirimycin groups." (PMID 28751809, 2017). "On the whole, the expressions of vimentin, EMA, SMA, and Bcl-2 were significantly different between carcinoma and sarcomatoid cells (P < 0.05)." (PMID 28449664, 2017). "Reports have stated that BCL-2 is a key regulator in chemotherapy resistance in several cancers, including GC." (PMID 27011182, 2016). "In this review, I attempt to provide an overview of the function of Bcl-2 proteins in the regulation of cancer cell invasion and metastasis." (PMID 26621844, 2016). "More recently, many reports support the evidence that BCL-2 acts to regulate cancer cell invasion and metastasis through mitochondrial metabolism." (PMID 27144561, 2016). "Inhibition of anti‐apoptotic Bcl‐2 protein has been shown to induce apoptosis as well as autophagy in cancer cells." (PMID 26648178, 2016). "Nevertheless, BCL2 inhibition is an attractive target for therapy, as illustrated by the fact that at least three BCL2 antagonists are currently undergoing clinical trials for cancer treatment." (PMID 26910115, 2016). "Bcl-2 protein, an antiapoptotic factor, is often deregulated in cancer and has become a promising anticancer drug target." (PMID 27502492, 2016). "One of the reasons for cancer cell resistance to apoptosis mediated by TRAIL is the overexpression of antiapoptotic proteins BcL-2 and/or Bcl-xL." (PMID 27338375, 2016). "The deregulation of Bcl2 family proteins mostly contributes to apoptosis evasion, suggesting that the inhibition of Bcl2 proteins is one of the most promising new approaches to targeted cancer therapy." (PMID 26830677, 2016). "Upregulation of various anti-apoptotic molecules, such as Bcl-2 and Bcl-xl, protects the cancer cells from induction of apoptosis." (PMID 27752089, 2016). "Concerning CD44+ cells (cancer stem-like cells), we can notice an overexpression of Bcl-2 (+100%) and Bcl-XL, at a lesser extend (+20%)." (PMID 26934442, 2016). "These anticancer strategies attempt to develop drug-designed inhibitors of anti-apoptotic proteins typically overexpressed in cancer cells, such as Bcl-2, Bcl-xL and IAPs." (PMID 27019364, 2016). "The significance of Bax to Bcl-2 ratio on the progression of several diseases or malignant tumors had been investigated by several studies." (PMID 27012679, 2016). "For the oncogenes, ES-fusion virtually extinguished the expression of both Bcl2 and C-fos in the adult cancer cells (Hepa1-6 and B16), as well as in the embryonic carcinomas (P19 and F9)." (PMID 27468690, 2016). "The down-regulation of Bcl-2 had been reported in other types of cancer cells treated with Matrine or Oxymatrine, two of the major components of CKI." (PMID 27602759, 2016). "Activation of NF-κB in cancer cells enhances their survival as a result of the upregulation of anti-apoptotic genes such as Bcl-xL, Bcl-2, c-IAP2, A1 and c-FLIP." (PMID 31051015, 2016). "For instance, miR-429 mediated suppression of EMT has also been correlated with miR-429 directly targets Onecut2, BMI-1 and E2F3, MiR-429 enhances cancer cell apoptosis under chemotherapy by targeting Bcl-2 and AP-2α." (PMID 27058893, 2016). "Due to the pro-apoptotic stresses that cancer cells encounter, anti-apoptotic Bcl-2 function is required for cell survival to counteract pro-apoptotic BH3-only protein function." (PMID 26833356, 2016).
cancer (continued). "The inhibition of PDK sensitizes both wild type and BCL-2-overexpressing cancer cells to radiation by interacting with BCL-2." (PMID 26593251, 2016). "Several anti‐apoptotic proteins such as Bcl‐2 and survivin which are known to be crucial for cancer cell survival are the downstream target genes of AKT and NF‐κB." (PMID 26648178, 2016). "To determine which BCL2 protein or proteins block apoptosis in different cancers, we computationally designed three-helix bundle protein inhibitors specific for each BCL2 pro-survival protein." (PMID 27805565, 2016). "This state has been termed as cancer cells “primed for death” and this dependence on anti-apoptotic BCL-2 proteins can be exploited to design more effective pro-apoptotic therapeutic strategies." (PMID 27455839, 2016). "Herb significantly increased the expression of Bax (p<0.001) and decreased Bcl-2 expression (p<0.05) in cancer cells." (PMID 27222827, 2016). "Because BMI1 and BCL2 have been reported as target genes of miR-15b in cancer, their mRNA levels in OvCa were also examined." (PMID 27195958, 2016). "Evasion of apoptosis is one of the hallmarks of cancer, as Bcl-2 factors are often overexpressed in malignant cells." (PMID 26973650, 2016). "Two cancer genes, namely the BCL2 (B-cell CLL/lymphoma 2) and the PTEN (Phosphatase and tensin homolog), were hub nodes in bioinformatics analyses." (PMID 27329603, 2016). "ABT-263 is a small molecule inhibitor for Bcl-2, Bcl-xL, and Bcl-w while ABT-199 is a specific inhibitor for Bcl-2, which is in clinical trials for cancer treatment." (PMID 27826299, 2016). "Anti-apoptotic protein Bcl-2 can inhibit the function of pro-apoptotic proteins by interaction and cancers with high levels of Bcl-2 show drug resistance in clinical cancer treatment." (PMID 27617998, 2016). "Delineation of the roles of pro-survival homologs in a given cancer, termed BCL2 profiling, aims to reveal which homolog or homologs a tailored treatment should target to maximize anti-cancer activity and minimize toxicity." (PMID 27805565, 2016). "Many cancer therapies kill cancer cells by activating Bax/Bcl-2/caspase or 3/PARP signaling, which increase cell death due to apoptosis, necrosis, autophagy, or pyroptosis." (PMID 27043621, 2016). "EGFR, VEGF, bcl-2 and survivin were expressed in the eight cancer cell lines, and siSp1,3,4 downregulated these gene products; however, the effects of siSp1, siSp3 and siSp4 were variable and there were also gene- and cell context-specific differences." (PMID 26967243, 2016). "A mitochondria targeted α-TOS nanoparticle formulation demonstrated enhanced cytotoxicity and mitochondrial activities in cancer cells by inhibiting Bcl2 protein and activating ATP synthase." (PMID 30034696, 2016). "Among these, the anti-apoptotic Bcl-2 protein is overexpressed in a variety of cancers where it enhances cell survival and can obstruct the efficacy of radiological and chemotherapeutic treatments of the cancer." (PMID 27578251, 2016). "The expression of individual Bcl-2 proteins in different types of cancer has been used as an independent prognostic marker." (PMID 26758417, 2016). "When one rationally designs drugs that target the bcl-2 G-quadruplex DNA for cancer chemotherapy, increased selectivity for G-quadruplex DNA and low cytotoxicity are key factors to consider in this process." (PMID 28773504, 2016). "B-cell lymphoma-2 (bcl-2) is an inner mitochondrial membrane protein, which can block programmed cell death, inhibit apoptosis, and participate in the survival of cancer cells." (PMID 27660759, 2016). "Bcl-2α is the more abundant isoform in both healthy and cancer cells and it remains dominant in cancer cells up-regulating Bcl-2 protein." (PMID 27494888, 2016).
cancer (continued). "The designs were used to determine the BCL2-dependence of different cancers, providing a more direct guide for therapy than knockdown/knockout strategies or mRNA analysis by mimicking the mechanism of action of BCL2-targeting small molecule drugs." (PMID 27805565, 2016). "Anti-apoptotic proteins such as B-cell lymphoma 2 (Bcl-2), B-cell lymphoma-extra large (Bcl-xl) and Mcl-1 are known to play key roles in cancer cell apoptosis." (PMID 26848531, 2016). "The ability of holo-Crabp1 to increase the Bax/Bcl-2 ratio also suggests a potential to sensitize resistant cancer cells to current therapies." (PMID 26935534, 2016). "We then examined the changes in levels of the Bcl-2 and Bax proteins that regulate the intrinsic apoptosis pathway of cancer cells." (PMID 27012679, 2016). "The broad expression of Bcl-2 in a variety of tumors, together with its function in resisting chemotherapy-induced apoptosis, makes bcl-2 a rational target for anti-cancer therapy." (PMID 28773504, 2016). "Jujube also dramatically increased the Bax/Bcl-2 mRNA ratio as high as six folds in treated cancer cells." (PMID 27222827, 2016). "The rationale behind mito-priming is based on earlier findings that some cancer cells are ‘primed for death' and require anti-apoptotic Bcl-2 function for survival." (PMID 26833356, 2016). "In recent years ongoing efforts have been made to identify novel inhibitors targeting Bcl2 expression in cancer cells to improve the outcome of anticancer therapy." (PMID 27105491, 2016). "On the other hand, Bcl-2 expression was found to correlate with that of ERα and PgR, i.e. with differentiated cancer phenotypes." (PMID 27538498, 2016). "The mechanistic action of current BH3 mimetics for cancer therapy is designed to block the binding between BCL2 and BIM, BAX and BAK." (PMID 27049723, 2016). "Further, the detection of RKO sensitivity to Bfl-1 inhibition highlights the capacity of the designed inhibitors to illuminate unique BCL2 profiles, even among cancers with similar general characteristics." (PMID 27805565, 2016). "Using our non-B DNA search algorithm, we systematically inspected the c-MYC and BCL-2 genes that are often involved in translocations in human cancers, for potential H-DNA- and Z-DNA-forming sequences." (PMID 27532010, 2016). "In our study, we observed pronounced suppression of the PI3K/AKT and NF-κB signaling pathways as well as Bcl-xL, Bcl-2, and survivin by ursolic acid, which made it a promising candidate for potential treatment of oxaliplatin-resistant cancers." (PMID 27472952, 2016). "Expression of Bcl-2 and other oncogenes is increased in cancer; this contributes to cancer cell survival." (PMID 27875990, 2016). "Bcl family (Bcl-2, Mcl-1), which are known to be crucial for cancer cell survival, are prominent targets for STAT3 and NFκB, and down-regulated as a consequence of STAT3 and NFκB inhibition." (PMID 27539371, 2016). "As expected, this increase of Bax to Bcl-2 protein ratio led to cleavage/activation of the key apoptosis co-ordination enzyme, caspase-3, in both of the two cancer spheres." (PMID 27012679, 2016). "Hower, Bcl-2 expression has a stronger impact as indicator of retained cancer differentiation, and of better disease outcome." (PMID 27538498, 2016). "Bcl-2 family, composed of proapoptotic (e.g., Bax and Bim) and antiapoptotic (e.g., Bcl-2) members, is important for regulation of cell death, apoptosis, tumorigenesis, and cellular responses to anti-cancer therapy." (PMID 27994550, 2016). "It is also possible that cancer cell reprogramming involves altering Bcl-2 proteins to sustain a metabolic phenotype suitable for increased growth." (PMID 26791262, 2016).
cancer (continued). "The P1 promoter, which is a GC-rich region that is capable of forming G-quadruplexes, is involved in the regulation of bcl-2 gene expression, and thus modulation of the appearance of cancer." (PMID 28773504, 2016). "Obatoclax, a pan-inhibitor of anti-apoptotic Bcl-2 proteins, exhibits cytotoxic effect on cancer cells through both apoptosis-dependent and -independent pathways." (PMID 26910910, 2016). "Next, we set out to define functional BCL2 dependency profiles of other cancer cell lines using a larger set of our designed inhibitors." (PMID 27805565, 2016). "The effects of honokiol on the increase of Bax to Bcl-2 ratio and subsequent apoptosis induction had been reported in various types of cancer cells." (PMID 27012679, 2016). "The similar phenomenon has also been reported in previous study (The study shows that Bcl-2/xL inhibitor ABT-263 induces cancer cell apoptosis while upregulates Mcl-1)." (PMID 27449090, 2016). "Expression of BCL2 is elevated in CSC-like populations and targeted BCL2 inhibitors selectively kill leukemic cancer stem cell populations." (PMID 26717985, 2016). "The protective roles of Se, such as upregulation of Bcl-2, cancer prevention and activation of cytokines, are well accepted." (PMID 27212152, 2016). "Because of their central role in maintaining cell viability, intense interest surrounds the targeting of anti-apoptotic Bcl-2 proteins in cancer." (PMID 26833356, 2016). "This is also confirmed by interrogation of the cancer genome atlas which reports Bcl-2 is amplified or mRNA upregulated in less than 3 % of cases." (PMID 27080533, 2016). "The pro‐survival members of the Bcl‐2 family, including Bcl‐2, Bcl‐xL, and Mcl‐1, are commonly overexpressed in a number of human cancers." (PMID 26696548, 2016). "Given these Bcl-2 select antagonists are well tolerated and performing well in adult cancer trials, they have high potential to translate to the pediatric setting to treat Bcl-2 dependent tumors." (PMID 26874859, 2016). "Pro-survival members promote, rather than suppress, ROS production in healthy cells, as confirmed by overexpression of Bcl-2, Bcl-XL, Bcl-w, and Mcl-1 in various types of normal and cancer cells, including bacteria." (PMID 26621844, 2016). "This comprehensive set of molecular probes should be useful to elucidate the molecular mechanisms of mitochondrial apoptotic pathways, determine BCL2 profiles of individual cancers, and provide a superior guide for tailored therapies." (PMID 27805565, 2016). "We established that LARP1 exerts this pro-survival effect, at least in part, by post-transcriptionally promoting the expression of BCL2, a well-characterized oncogenic anti-apoptotic protein and a promoter of cancer cell survival." (PMID 26717985, 2016). "To address the first question, we took some insight from the cancer models, where Bcl-2 overexpression is the etiological factor." (PMID 27826299, 2016). "Under normal conditions, BET family proteins perform transcription regulatory functions, while in cancer, they can upregulate aberrant transcription of key oncogenes such as cMYC, BCL-2, and IRF4." (PMID 27903272, 2016). "Previous studies have demonstrated that MAPK pathway is active in Bcl-2 overexpressing cancer cells under stressful conditions." (PMID 26840298, 2016). "A representative cancer cell line (HeLa) was engineered to overexpress Mcl-1, Bcl-2 or Bcl-xL, and we assayed the activity of the designed inhibitors in each setting." (PMID 27805565, 2016).